AP4E1 (adaptor related protein complex 4 subunit epsilon 1)
Description:
Component of the adaptor protein complex 4 (AP-4). Adaptor protein complexes are vesicle coat components involved both in vesicle formation and cargo selection. They control the vesicular transport of proteins in different trafficking pathways. AP-4 forms a non clathrin-associated coat on vesicles departing the trans-Golgi network (TGN) and may be involved in the targeting of proteins from the trans-Golgi network (TGN) to the endosomal-lysosomal system. It is also involved in protein sorting to the basolateral membrane in epithelial cells and the proper asymmetric localization of somatodendritic proteins in neurons. AP-4 is involved in the recognition and binding of tyrosine-based sorting signals found in the cytoplasmic part of cargos, but may also recognize other types of sorting signal (Probable).
Synonyms: AP-4-EPSILON; SPG51; CPSQ4; STUT1
Tractability: Antibody: UniProt places it where antibodies can reach, with high confidence. PROTAC: ubiquitination databases record sites on it; its protein half-life has been measured.
Gene: Protein-coding gene on chromosome 15 (50,908,672 to 51,005,895, forward strand). Ensembl gene ENSG00000081014.
Subcellular location: Golgi apparatus, trans-Golgi network membrane
Pathways (Reactome):
Vesicle-mediated transport: Golgi Associated Vesicle Biogenesis; Lysosome Vesicle Biogenesis
Gene Ontology:
Molecular function: protein binding; cargo adaptor activity
Biological process: intracellular protein localization; protein targeting; vesicle-mediated transport; establishment of protein localization; intracellular protein transport; protein transport
Cellular component: AP-4 adaptor complex; endosome lumen; trans-Golgi network; trans-Golgi network membrane; Golgi apparatus; membrane coat
Genetic constraint (gnomAD): Loss-of-function variants: 52 observed, 113.72 expected, observed/expected ratio (o/e) 0.46, 90% interval 0.37 to 0.58. The upper end of that interval is the gene's LOEUF score, 0.58, which puts it in group 2 of 6, group 1 being the genes least tolerant of losing a copy. Missense variants: 1,250 observed, 1,286.1 expected, observed/expected ratio (o/e) 0.97, 90% interval 0.93 to 1.02. Synonymous variants: 455 observed, 467.88 expected, observed/expected ratio (o/e) 0.97, 90% interval 0.9 to 1.05.
Gene-disease validity (ClinGen):
ClinGen rates the evidence that AP4E1 causes each of these diseases.
AP-4 deficiency syndrome (autosomal recessive): Definitive. A genetic disorder associated with variation(s) in the AP4 genes: AP4B1, AP4E1, AP4M1, and AP4S1.
Homologues: Orthologues: chimpanzee AP4E1 (99% identical), macaque AP4E1 (97% identical), dog AP4E1 (90% identical), pig AP4E1 (90% identical), rabbit AP4E1 (89% identical), guinea pig AP4E1 (85% identical), rat Ap4e1 (81% identical), mouse Ap4e1 (80% identical), tropical clawed frog ap4e1 (60% identical), zebrafish ap4e1 (53% identical), Drosophila melanogaster AP-2alpha (17% identical), Caenorhabditis elegans apa-2 (17% identical). Paralogues in human: AP2A2 (18% identical), AP1G1 (18% identical), AP2A1 (18% identical), AP1G2 (17% identical).
Diseases named in the same sentence as AP4E1 in open-access papers:
AP4E1 is named in the same sentence as 26 diseases in open-access papers, as found by Europe PMC text mining. Sharing a sentence is not in itself a finding about the gene and the disease. The quoted sentences say what the papers report.
hereditary spastic paraplegia (6 papers, 2013 to 2025). Hereditary spastic paraplegias (HSP) comprise a genetically and clinically heterogeneous group of neurodegenerative disorders characterized by progressive spasticity and hyperreflexia of the lower limbs. "Ap4e1 deficiency has been tied to cerebral palsy syndrome, speech deficits and hereditary spastic paraplegia." (PMID 34064652, 2021). "Indeed, mutations in genes encoding all subunits of AP-4 (ε1; AP4E1, β1; AP4B1, μ1; AP4M1 and σ1; AP4S1) have been identified as leading to a complex form of hereditary spastic paraplegia (HSP) termed AP-4 deficiency syndrome (henceforth AP-4 deficiency)." (PMID 31142229, 2020).
Intellectual disability (5 papers, 2013 to 2023). "The aim of the current study was to characterize the phenotype of a paediatric patient with an identified novel AP4E1 mutation presenting with significant psychomotor retardation, intellectual disability and paraplegia." (PMID 34006278, 2021). "For instance, most subtypes of CP that involve mental retardation are induced by recessive variations in the genes of 4 protein-binding complexes (AP4M1, AP4E1, AP4S1, and AP4B1)." (PMID 36323241, 2023).
Spastic paraplegia (5 papers, 2013 to 2026). Complete loss of the ability to move the lower limbs accompanied by spasticity of the lower limbs. "Similarly, biallelic loss-of-function variants in AP4E1 cause spastic paraplegia, while a haplotype of two missense variants as well as heterozygous variants have been associated with stuttering." (PMID 40836029, 2026). "A comprehensive mutational analysis (including resequencing), as well as an analysis of AP4E1 in other individuals with spastic paraplegia and in their families, should be undertaken to evaluate the frequency of this disorder." (PMID 34006278, 2021).
virus infection (2 papers, 2021 to 2024). "This showed virus infection led to redistribution of AP4E1, and by inference AP-4 complexes, away from its characteristic trans-Golgi location, to occupy regions of the cell where GP-1 and in particular NP was most abundant, suggestive of a close interaction between these components." (PMID 38334330, 2024).
ciliopathy (1 paper, 2022). A genetic disorder of the cellular cilia or the cilia anchoring structures, the basal bodies, or of ciliary function. "Histological and morphological evidence of phenotypes found in ciliopathies in knockout mouse lines are presented as examples (genes Abi2, Wdr62, Ap4e1, Dync1li1, and Prkab1)." (PMID 36456625, 2022). "Five of these genes predicted to have ciliary interaction (Abi2, Wdr62, Ap4e1, Dync1li1, and Prkab1) had abnormal morphological features detected by imaging that are consistent with the spectrum of phenotypes observed in ciliopathies." (PMID 36456625, 2022). "Abi2, Ap4e1, and Prkab1 therefore have strong evidence to be novel candidate ciliopathy genes." (PMID 36456625, 2022).
Hydrocephalus (1 paper, 2025). Hydrocephalus is an active distension of the ventricular system of the brain resulting from inadequate passage of CSF from its point of production within the cerebral ventricles to its point of absorption into the systemic circulation. "More patients have mild ventricular enlargement caused by non‐hydrocephalus causes, e.g. SPG47/AP4B1, SPG50/AP4M1, SPG51/AP4E1." (PMID 39932116, 2025).
melanoma (1 paper, 2021). A malignant, usually aggressive tumor composed of atypical, neoplastic melanocytes. "AP4E1 (associated with MEL in our work) is found in COSMIC which means that it does exhibit mutations in melanoma." (PMID 34570764, 2021). "In the case of melanoma (MEL), high novelty targets are SPPL2A, CHL1, AP4E1, SECISBP2L, and COPS2." (PMID 34570764, 2021).
neuroblastoma (1 paper, 2018). Neuroblastoma (NB) is the most common solid, extracranial childhood tumor. "To determine whether ATG9A is similarly affected by loss of AP-4 in a cell line more relevant to the neuronal phenotypes of AP-4 deficiency, we used CRISPR/Cas9-mediated gene editing to deplete AP4B1 or AP4E1 in mixed populations of SH-SY5Y neuroblastoma cells." (PMID 30262884, 2018).
neurodevelopmental disorder (2 papers, 2020 to 2026). A behavioral and cognitive disorder with onset during the developmental period that involves impaired or aberrant development of intellectual, motor, or social functions. "Homozygous mutations in AP4E1 are a cause of hereditary spastic paraplegia, a neurodevelopmental disorder characterized by developmental delay, moderate to severe intellectual disability and neonatal hypotonia that progresses to spasticity." (PMID 40836029, 2026). "Even though the genes AP4E1 and ZBTB20 have previously been linked to stuttering and separately to neurodevelopmental disorders, the mode of inheritance (i.e. dominance/recessivity) do not overlap." (PMID 40836029, 2026).
infection (1 paper, 2021). The state of being infected such as from the introduction of a foreign agent such as serum, vaccine, antigenic substance or organism. "In contrast, all proteins tested were expressed to the approximate levels of control cells in CHMP4C- and AP4E1-depleted cells, confirming that the virus replication cycle was blocked late in infection in the absence of these factors." (PMID 33975940, 2021).
tumor (1 paper, 2021). "AP4E1 encodes a protein that plays important roles in the secretory and endocytic pathways which are important for cell communication in the tumor microenvironment." (PMID 34570764, 2021).
AP4E1 also shares sentences with these, for which no sentence is quoted: microcephaly (3 papers); cancer (2); Batten disease (1); Cognitive impairment (1); congenital cataracts (1); congenital muscular dystrophy (1); generalized epilepsy (1); Global developmental delay (1); learning disabilities (1); Macrocephaly (1); nocturnal frontal lobe epilepsy type 1 (1); paraplegia (1); spastic paraplegia 51 (1); Spasticity (1); Walker-Warburg syndrome (1).